MMP7 (matrix metallopeptidase 7)
Diseases named in the same sentence as MMP7 in open-access papers (continued):
Sharing a sentence is not in itself a finding about the gene and the disease.
adenoma (12 papers, 2003 to 2023). A neoplasm arising from the epithelium. "Consistent with this, the Wnt target genes MMP7 and Tenascin-C, which are expressed at high levels in benign human adenomas and early colon cancer stages, were upregulated in pre-malignant tissue of gpA33ΔN-Bcat mice." (PMID 26398937, 2015). "MMP7 also showed some differences for adenomas (p = 0.0092), but showed an opposite direction to the expected one." (PMID 25215506, 2014). "Although both enzymes were expressed at high levels in the Min adenomas, in situ and immunohistochemistry localised MMP-7 specifically to the neoplastic epithelial cells, while COX-2 was localised to the superficial stroma within the adenoma." (PMID 12778076, 2003). "We have previously shown that 70 – 90% of Min adenomas express MMP-7 in the neoplastic epithelium and that Min mice null for MMP-7 have 58% fewer tumours than Min mice with wild-type MMP-7." (PMID 12778076, 2003). "Although in Min/+ mice, MMP7 mRNA was detected in 88% of Min adenomas and localized to epithelial-derived tumor cells, MMP7-deficient mice with a targeted disruption of the gene had a 60% reduction in mean tumor multiplicity and decreased average tumor diameter." (PMID 36677584, 2023). "Thus, we concluded that the MMP-7 gene overexpression has a critical role in colorectal adenoma angiogenesis and could be a primary event in the adenoma-carcinoma sequence." (PMID 34944846, 2021). "Matrix metalloproteinase-7 (MMP7) also showed a significant association but was not further considered because it was due to an underexpression in adenomas compared to controls, which represented the opposite sense of differential expression that we were trying to validate." (PMID 25215506, 2014). "Additionally, MMP-7 is overexpressed in 90% of adenomas from patients with FAP." (PMID 12778076, 2003). "Interestingly, despite the proven association with CAC, TIMP1, MMP7, and ADAM8 were activated in IBD-affected colon tissues, which is fully in line with our data: the high expression of these genes was demonstrated in DSS-inflamed and adjacent to adenomas colon tissues in mice." (PMID 36901742, 2023). "We found that the expression levels of MMP-7 and VEGF-A genes were higher in villous adenoma than in other types of adenomas." (PMID 34944846, 2021). "Four DEGs (MMP-7, MYC, WNT-5A, and AXIN2) were upregulated in tumor vs. normal tissues, or adenoma vs. normal tissue in TCGA, which was overlapped with our data." (PMID 32258125, 2020). "Overexpression of MMP-7 represents the early carcinogenesis of CRC and formation of adenoma from normal colorectal mucosa thus, it can be considered as a prognostic factor in the diagnosis of CRC." (PMID 29930913, 2018). "Even for pre-cancerous adenomas, the combination of HERV-H Xp22.3 and MMP7 reaches values of 71% and 81%, respectively." (PMID 26517682, 2015). "In addition to MMP-7 expression, 60–65% of Min adenomas express MMP-2 and MMP-10 (stromelysin-2) and 50% express MMP-3 and MMP-13 (collagenase) with expression limited to the stroma surrounding the adenoma." (PMID 12778076, 2003).
cervical carcinoma (12 papers, 2018 to 2025). A carcinoma arising from either the exocervical squamous epithelium or the endocervical glandular epithelium. "The diagnostic potential of MMP-7 has also been noted for several gynecologic cancers such as ovarian cancer, endometrial cancer and cervical cancer." (PMID 37048701, 2023). "Moreover, the MMP-7 rs11568818 was evidently associated with a higher cervical cancer (CC) incidence in Asians (allelic model, OR = 1.372, 95% CI = 1.148–1.640, p = 0.001; dominant model, OR = 1.381, 95% CI = 1.088–1.753, p = 0.008; recessive model, OR = 1.664, 95% CI = 1.175–2.357, p = 0.004)." (PMID 35574300, 2022). "For cervical cancer, SE for MMP-7 was lower than that for the routinely used marker SCC-Ag, while SP was higher than SCC-Ag." (PMID 40332487, 2025). "Elevated MMP7 levels correlate with higher cancer grade, clinical stage, and metastasis in cervical cancer, suggesting its potential as a clinical biomarker for the disease." (PMID 40168262, 2025). "This study found that calcitriol significantly suppressed MMP7 mRNA expression in CaSki cervical cancer cells, an effect also observed in other cancer types." (PMID 40168262, 2025). "The highest AUC value in cervical cancer patients was obtained by MMP-7 (0.9878), which greatly surpasses the results of standard comparative markers CA 125 (0.6870) and SCC-Ag (0.7352)." (PMID 41462922, 2025). "In this study, MA has been shown as a potential candidate against cervical cancer by suppressing the expression level of MMP-7, β-catenin, c-Myc, and cyclin D1 in Wnt signaling cascade." (PMID 34421589, 2021). "Matrix metalloproteinase 7 (MMP7) has been reported to be a marker for a discrete population of cells at the squamocolumnar junction that contributes to cervical cancer." (PMID 29944714, 2018). "Therefore, this confirms our reports using a test material other than blood, making MMP-7 a good candidate for a biomarker of cervical cancer." (PMID 41462922, 2025). "Thus, it seems that part of the beneficial effects of calcitriol on cervical cancer may be attributed to its suppression of MMP7 and MMP-13 gene expression." (PMID 40168262, 2025). "Regarding the mechanism, MA might attenuate the proliferation of cells by downregulating the expression level of MMP-7, β-catenin, cyclin D1, and c-Myc and considerably attenuating apoptotic process in cervical cancer cells through Wnt/β-catenin signaling cascade." (PMID 34421589, 2021). "MMP-7 and MMP-10 not only differentiate cervical cancer from dysplasia and healthy controls but also reflect disease stage, supporting their potential clinical application as sensitive and specific serum biomarkers." (PMID 41462922, 2025). "MMP-7 and MMP-10 showed the most pronounced increases in cervical cancer patients, with median concentrations rising progressively from cervical dysplasia to early-stage (I–II) and advanced-stage (III–IV) cancer." (PMID 41462922, 2025). "NaB alone up-regulated MMP2, MMP7 and MMP9 expression, and promoted the migration and invasion of cervical cancer cells." (PMID 36338704, 2022).
Obesity (12 papers, 2014 to 2026). Accumulation of substantial excess body fat. "When subjects were categorized according to severity of obesity, the frequencies of MMP-7 -181G variant were higher in morbidly obese subjects." (PMID 29317790, 2017). "In the current report, when individuals were stratified by BMI, the MMP-3 45Glu (G) and MMP7 (-181G) variants were more frequent in individuals with severe forms of obesity." (PMID 29317790, 2017). "The current findings also highlight a significant correlation between the MMP-3Lys45Glu (A/G) and MMP-7 (-181A/G) variants and severe forms of obesity among Tunisians." (PMID 29317790, 2017). "In summary, BBOX1, SSTR1, MMP7, and LACC1 are identified as diagnostic markers of obesity and NAFLD." (PMID 39619480, 2025). "In this study, variants in MMP7 (-181G) and MMP12 (-82G) were also associated with obesity and its severity." (PMID 37445827, 2023). "Expression levels of MMP7 in obesity is controversial and contradictory results were reported in a number of studies." (PMID 37445827, 2023). "MMP-3 Lys45Glu (A/G), MMP-7 (-181A/G), and MMP-12 (-82A/G) variants were associated with obesity and its anthropometric indicators." (PMID 29317790, 2017). "The impact of MMP-1 (-519A/G, -1607 1G/2G), MMP-3 Lys45Glu (A/G), MMP-7 -181A/G, and MMP-12 -82A/G variants and plasma MMP levels on obesity and microvascular reactivity in Tunisians." (PMID 29317790, 2017). "When subjects were categorized according to severity of obesity, a higher level of MMP-7 was observed in morbidly obese subjects carrying the -181G variant (AG+GG: 0.32 (0.31–0.6), AA: 0.18 (0.17–0.24), P = 0.01, Pc = 0.04)." (PMID 29317790, 2017). "Other reports demonstrated that MMP-7 levels positively correlate with fat diameter, as well as with markers of central obesity and obesity-related metabolic traits." (PMID 29317790, 2017). "Specifically, mouse models of obesity have showed that the expression of MMP7 is down regulated in obesity." (PMID 24886386, 2014). "Studies indicate that MMP7 has the ability to attenuate its classical functions and antioxidant properties in lipid metabolism by cleaving apoA-IV, which may lead to obesity." (PMID 39619480, 2025). "Second, MMP7 expression levels (and of COL6A3 encoding collagen VI alpha) were found to be increased in ScWAT of obese insulin resistant subjects as compared with obese-insulin sensitive subjects, suggesting an involvement of MMP7 in obesity, ECM remodeling and insulin resistance." (PMID 37445827, 2023). "Is the NT/MMP7/DEFA5 axis deregulated in adipose tissue during human obesity development?" (PMID 37445827, 2023). "The current study is the first to report upregulation of MMP7 mRNA expression which contrasts with previous reports of decreased expression in murine obesity and decreased circulating concentrations in human obesity." (PMID 35958557, 2022). "MMP-3, MMP-7, and MMP-12 polymorphisms associate with obesity risk and its severity." (PMID 29317790, 2017). "Previous studies demonstrated that decreased levels of MMP-7 may be considered as a marker of obesity." (PMID 29317790, 2017). "The aims of the current study were, therefore, to assess the impact of MMP-1-519A/G (rs1144393), MMP-1 -1607 1G/2G (rs1799750), MMP-3Lys45Glu (A/G) (rs679620), MMP-7 -181A/G (rs11568818), and MMP-12 -82A/G (rs2276109) polymorphisms on obesity status and its anthropometric indicators." (PMID 29317790, 2017). "Alterations of MMP-7 levels in obesity could also be related to genetic variations in MMP-7 gene." (PMID 29317790, 2017). "Obesity and NAFLD share a molecular mechanism with BBOX1, SSTR1, MMP7, and LACC1, which play crucial roles in disease development and can serve as common predictors." (PMID 39619480, 2025). "BBOX1, SSTR1, MMP7, and LACC1 emerged as common predictors for obesity and NAFLD through animal experimentation and predictive model analysis." (PMID 39619480, 2025).
Obesity (continued). "The goals of the current report were to explore the impact of MMP-1 (-519A/G; -1607 1G/2G), MMP-3 Lys45Glu (A/G), MMP-7 -181A/G, and MMP-12 -82A/G SNPs on the development of obesity and its severity among Tunisians." (PMID 29317790, 2017). "Among MMPs, MMP-1, MMP-3, MMP-7, and MMP-12 genes have been found to affect adipose tissue remodeling and obesity-related metabolic traits." (PMID 29317790, 2017). "Notably, ChrSd supplementation lowered the hepatic expression of genes previously reported to be candidate genes for obesity, such as Insig-1, lepR, neurotrophic tyrosine kinase receptor type 2 (Ntrk2), melanocortin 5 receptor (Mc5r), and matrix metallopeptidase 7 (Mmp7)." (PMID 27977712, 2016). "Of note, MMP-7 and MMP-9 were highly upregulated by 42.5 and 16.3 fold in obesity, respectively." (PMID 35958557, 2022). "However, in two animal models of genetic obesity (ob/ob and db/db) and in a HFD model, while mRNA levels for MMP2, MMP3, MMP12, MMP14, MMP19, and TIMP1 are robustly induced, MMP7 (and MMP3) transcripts are markedly reduced in obese visceral adipose tissue compared to lean tissue." (PMID 37445827, 2023).
rheumatoid arthritis (12 papers, 2015 to 2025). A chronic, systemic autoimmune disorder characterized by inflammation in the synovial membranes and articular surfaces. "SP-D in combination with MMP-7 can facilitate the identification of rheumatoid arthritis associated ILD at an early stage." (PMID 35789314, 2022). "For example, MMP-7 has been suggested as a marker of ILD in patients with rheumatoid arthritis and systemic sclerosis." (PMID 39521375, 2025). "Consistent with our finding, neutrophil infiltration has been detected more extensively in biopsies with high MMP-7 expression in patients with rheumatoid arthritis." (PMID 35933374, 2022). "Higher serum MMP7 has been found in IPF compared to other ILDs, as well as in patients with rheumatoid arthritis (RA) with ILD (RA-ILD), and is a marker of progression in IPF and fibrotic hypersensitivity pneumonitis (fHP)." (PMID 41049336, 2025). "MG63 cells treated with serum from ankylosing spondylitis patients had higher PPARD, fra-1, MMP7 and OPG gene expression than did cells treated with serum from controls or rheumatoid arthritis patients (all p<0.05)." (PMID 26602520, 2015).
asthma (11 papers, 2009 to 2024). "For instance, mmp7−/− mice developed an attenuated asthmatic phenotype and airway epithelial expression of MMP-7 was critical for development-asthma like disease." (PMID 20596522, 2010). "In the antigen induced airway inflammation model, which has been shown to exhibit aspects similar to the inflammation observed in asthma, MMP-7 mRNA levels were found to be increased as early as 4 hours after ovalbumin challenge." (PMID 19650897, 2009). "Although the roles of MMP-7 and MMP-10 in asthma are still being elucidated, MMP-9 has shown consistent associations with disease severity and airway remodeling processes." (PMID 38275403, 2024). "MMP-7, MMP-9, and MMP-10 are important in asthma, particularly in airway remodeling and extracellular matrix alterations." (PMID 38275403, 2024). "They further demonstrated that TGF-β1 released from eosinophils further induced MMP-2, MMP7, MMP9 and MMP12 which are all essential for abnormal matrix turnover and myofibroblast differentiation in asthma fibrosis." (PMID 36911735, 2023). "The Western blotting results also showed that Sin obviously suppressed the expressions of MMP7 and MMP9 in the lungs of the mice with asthma." (PMID 34804018, 2021). "Sin also inhibited MMP7, MMP9, and vimentin expression in 16HBE cells and respiratory epithelial cells from mice with asthma." (PMID 34804018, 2021). "UPM stimulation decreased MMP7 mRNA expression in triple-co-cultures with moMφs (UPM 24 h) (1.0 fold change (− 6.3 to 2.6 fold change)) compared to untreated epithelial cells alone (5.6 fold change (3.3 to 11.5 fold change), p = 0.049) in the asthma group." (PMID 34168212, 2021). "A key observation in our study was that MMP-7, MMP-9, and MMP-10 concentrations remained similar across all the investigated groups, indicating that they may not possess any prognostic value in asthma." (PMID 38275403, 2024).
cholestasis (11 papers, 2020 to 2025). Impairment of the bile flow caused by obstruction within the liver, or outside the liver in the bile duct system. "Also, receiver operating characteristic analysis showed that a serum MMP-7 level of > 1.43 ng/mL was predictive of BA in infants with cholestasis (diagnostic accuracy, 88%)." (PMID 35717157, 2022). "Also, in the mentioned study, the level of MMP7 for other causes of cholestasis was 4.4 ng/ml, but in our study it had an average of 4.73." (PMID 35717157, 2022). "Furthermore, the cut off value for differentiating BA from other causes of cholestasis was 10.37 ng/ml, while in our study this cut-off point was 7.8 for MMP7 and 434.5 for GGT." (PMID 35717157, 2022). "Our data provides valuable insight into the interpretation and potential limitations of MMP-7 in infants with both cholestasis and congenital heart disease." (PMID 39483898, 2024). "Patients with CHD-C, particularly those with medically treated PH, had significantly higher MMP-7 levels compared to infants with cholestasis alone." (PMID 39483898, 2024). "Serum MMP-7 levels in infants with CHD-C were significantly elevated compared to those with cholestasis alone." (PMID 39483898, 2024). "Median MMP-7 levels were higher in the CHD-C group than the cholestasis alone group [50 ng/mL (IQR 38–95 ng/mL) vs. 34 ng/mL (IQR 23–79 ng/mL), p=0.009]." (PMID 39483898, 2024). "This is a single center cross sectional study including infants <180 days of age with cholestasis and serum MMP-7 levels collected from 2019–2023." (PMID 39483898, 2024). "The median MMP-7 level in the CHD-C group was below the established cut-off for BA but was significantly higher than that of the cholestasis alone group." (PMID 39483898, 2024). "The primary aim of the study was to quantify serum MMP-7 level expression in neonates and infants with concurrent cholestasis and CHD and to compare those levels with patients who solely had cholestasis." (PMID 39483898, 2024). "The results of a study showed that infants with BA had a significantly higher serum MMP-7 level than that of non–BA infants with cholestasis of equivalent age." (PMID 35717157, 2022). "The serum MMP-7 is accurate and reliable in differentiating BA from non-BA cholestasis, showing its potential application in the diagnostic algorithm for BA and significant role in the future research regarding pathogenesis of BA." (PMID 38978022, 2024). "Also, considering that before MMP7, Gamma-glutamyl transferase (GGT) was used as a suitable biomarker to differentiate these two diagnoses (BA than other causes of cholestasis), we compared specificity & sensitivity and diagnostic accuracy of these two biomarkers." (PMID 35717157, 2022). "MMP-7 could reflect the early stage of bile duct injury before the bile duct obstruction develops." (PMID 35717157, 2022). "From December 2020 to October 2021, 241 infants with cholestasis undertook both serum and DBS MMP-7 measurement." (PMID 38034822, 2023). "Despite this, serum MMP-7 is regarded as an indirect but objective parameter in discriminating BA from other non-BA cholestasis." (PMID 41217622, 2025). "The sensitivity and specificity of MMP7 to differentiate (diagnose) BA from non-BA cholestasis in our study was 95.5% and 94.5%, respectively." (PMID 35717157, 2022). "The mean serum MMP7 levels in BA, non-BA cholestasis and control group was 15.91 ± 6.64, 4.73 ± 2.59 and 0.49 ± 0.33, respectively." (PMID 35717157, 2022). "The mean serum MMP7 levels in BA, non-BA cholestasis and control group was 15.91 ng/ml ± 6.64, 4.73 ng/ml ± 2.59 and 0.49 ng/ml ± 0.33, respectively." (PMID 35717157, 2022). "We investigated the utility of MMP-7 in discriminating BA from non-BA cholestasis in infants with CHD and whether MMP-7 elevation was present in infants requiring treatment for clinically significant PH." (PMID 39483898, 2024). "The difference in serum levels of MMP-7 and GGT between BA and non-BA cholestasis were 11.18 and 277.69, respectively." (PMID 35717157, 2022).